SOD2 (superoxide dismutase 2)
Diseases named in the same sentence as SOD2 in open-access papers (continued):
Sharing a sentence is not in itself a finding about the gene and the disease.
infection (continued). "Based on the our assumption that AAV can provoke oxidative stress in MSC, we analyzed the mRNA expression of two antioxidant enzymes: Peroxiredoxin 5 (PRDX5) and Mn superoxide dismutase (SOD2), SERPINB2 and HSP90 in human MSC after 7 days post infection." (PMID 34494647, 2021). "A majority (64/92) of NF-κB signaling pathway genes were downregulated more than 2-fold with infection, whereas only 5 of 92 were upregulated, BCL2A1, IL1B, CXCL8, MMP9, and SOD2." (PMID 33194960, 2020). "In a cell culture model, during the first hours after infection, SOD1, SOD2, glutathione S-transferase (GST), CAT, and GPx are induced." (PMID 33381273, 2020). "Gene expression analysis of mitochondrial SOD2 transcripts in BE2C cells after a 30 min, 2 h, and 24 h infection was performed." (PMID 32466166, 2020). "Infection with ST resulted in substantial reduction in the expression of SOD-1, SOD-2, catalase and GADD45A, perhaps to allow ROS levels to build-up to control the pathogen." (PMID 27599659, 2016). "The reduction of SOD-1, SOD-2, catalase and GADD45A was much more pronounced in the livers of FoxO3a−/− mice following infection with ST." (PMID 27599659, 2016). "Among the genes present in this overlap were interleukin 1 beta, a proinflammatory cytokine shown to be involved in infection-related PTB and PE, and superoxide dismutase 2, an antioxidant enzyme shown to be involved in oxidative stress associated with PTB." (PMID 26044726, 2015). "Superoxide dismutase 2 (SOD2) and ATF3 are important anti-oxidative genes that were up-regulated to a greater extent in COPD pBECs after infection when compared with infected healthy pBECs." (PMID 23384071, 2013). "Consistent with a central role for oxidative stress responses in cell-intrinsic responses to infection, key antioxidant enzymes (GSR, CAT, GPX1, and PRDX1) were downregulated by YFV-17D and select genes (SOD2, NFE2L2, and KEAP1) were upregulated by MnTBAP treatment." (PMID 39282299, 2024). "Finally, while the murine infection models suggest Cuf1 regulation of SOD2 does not affect the virulence of C. neoformans, this regulation does appear to impact the ability of C. neoformans to colonize Cu deficient niches, including the brain and kidneys, during acute stages of infection." (PMID 33567338, 2021). "In addition, we observed that the VDAC1 mRNA levels did not change as a result of any of these treatments, while overexpression of SOD2 and OGG1 was shown to significantly increase each of the related mRNA levels, indicating successful infection." (PMID 33423158, 2021). "Actually, we had already noticed that infection with the wild-type EPEC E2348/69 strain did not enhance expression of SOD2 (an HIF-2α-specific downstream gene) in HCT116 cells under hypoxia." (PMID 30125331, 2018). "Sod1−/− but not Sod2+/− or Sod3−/− mice lost more body weight compared to WT mice, which started in the early phase of infection." (PMID 26588782, 2015). "Therefore, to elucidate the mechanism of the suppressed Sod2 gene expression in prion-infected cells after IAV/WSN infection, we investigated NF-κB nuclear translocation in N2aC24 and N2aC24L1-3 cells after IAV/WSN infection." (PMID 39194237, 2024). "Furthermore, we show that infection with WT but not Δβ2.7 virus results in strong upregulation of a cellular antioxidant enzyme, superoxide dismutase 2 (SOD2) in CD14+ monocytes." (PMID 35215840, 2022). "Overall, the reduction of SOD2 did not influence neuronal function upon challenge with infection, disease duration, or the appearance of the neuropathology and severity of the spongiform pathology across different brain regions in response to infection with different prion strains." (PMID 34735539, 2021).
infection (continued). "Since the WT protein intensities of SOD2 were variable across all infections and neither WT SOD2 protein levels nor the reduced levels in the SOD2+/- mice influenced the outcome of the disease, fluctuations of SOD2 protein levels appear to be a secondary effect of the disease process." (PMID 34735539, 2021). "Similarly, infection of NSC34 cells with adenoviral hSOD1G93A induces oxidative stress, mitochondrial dysfunction and intrinsic apoptosis, which are significantly alleviated by co-expression of the mitochondrial antioxidant enzymes, SOD2 and GSH peroxidase-4." (PMID 26785244, 2014). "Consequently, we analysed cellular SOD2 levels during infection in the presence or absence of β2.7." (PMID 35215840, 2022). "Again, Sod1−/− mice, but neither Sod2+/− nor Sod3−/− mice, showed highly elevated concentrations of ALT within the first 2 days of infection." (PMID 26588782, 2015). "However, Sod2 mRNA was increased in N2aC24 cells, but not in N2aC24L1-3 cells, after IAV/WSN infection." (PMID 39194237, 2024). "While SOD2 was reported to be upregulated in infected Vero cells, we observed lower expression after the infection of moMΦ, and no alteration in WSL, indicating that the ASFV-induced regulation of SOD2 could be cell-type-specific." (PMID 34835004, 2021). "Consistently, under hypoxia, the infection of the wild-type EPEC E2348/69 strain induced the expressions of PDK1, PGK1, SLC2A1 (GLUT1), and PKM2, four well-defined HIF-1α targets, but did not induce the expression of SOD2, a well-defined HIF-2α target." (PMID 30125331, 2018). "The addition of IFNγ after infection not only resulted in a dramatic increase of the translation of the before mentioned genes but also in the translation of IFNß1, IL12ß, MIP1 and CCL3, CCL4, NOS2 and SOD2, and FAS but, nevertheless, did not prevent multiplication of the bacteria." (PMID 32462327, 2020).
neurodegenerative disease (39 papers, 2009 to 2025). A disorder of the central nervous system characterized by gradual and progressive loss of neural tissue and neurologic function. "Human SOD2 mutations are suggested to link to neurodegenerative diseases and conditions, although these associations are less clear than the ALS-links of SOD1." (PMID 40904733, 2025). "SOD2 was found to play a role in neurodegenerative disease according to the Disease Ontology database, a polymorphism in the sod2 gene was associated with differences in white matter microstructure and suboptimal brain aging." (PMID 38267423, 2024). "Abnormal expression of Nrf2, GCLc, SOD1, and SOD2 has been reported to be associated with PD and other neurodegenerative diseases." (PMID 29234413, 2017). "This might suggest a common behavior of SOD2 in neurodegenerative diseases associated with FeS clusters deficiency, leading to a lower tolerance to oxidative stress." (PMID 41372147, 2025). "The loss of SOD2 plays a critical role in the progression of neurodegenerative diseases." (PMID 36582614, 2022). "Several protein groups associated with aging and neurodegenerative diseases including apolipoprotein E (ApoE), S100B, Sod1, Sod2, huntingtin (Htt), macrophage migration inhibitory factor (Mif), α-Synuclein (Snca) were modulated by either drug treatment or the behavioural training per se." (PMID 34907284, 2021). "Superoxide dismutase (SOD2) is a potent mitochondrial antioxidant in neurodegenerative diseases, which increased." (PMID 39055937, 2024). "The enzyme SOD2, the mitochondrial isoform, is of particular importance for neurodegenerative diseases." (PMID 38672073, 2024). "The SOD1, SOD2, and FIS1 genes of yeast cells are homologous to those in humans, and mutation or change of expression of these genes in humans is related to neurodegenerative diseases." (PMID 36829855, 2023). "Previous studies have reported a disruption in SOD activities and mutations in SOD-1 and SOD-2, genes encoding SOD in neurodegenerative diseases." (PMID 37381025, 2023). "SOD2, an enzyme that converts superoxide to less reactive hydrogen peroxide and diffuse freely, is strongly involved in the progression of neurodegenerative diseases." (PMID 37255932, 2023). "Studies found that Sirt3 increases the anti-oxidant capacity of cells by deacetylating mitochondrial proteins including SOD2 in age-related diseases such as neurodegenerative diseases and cardiovascular diseases." (PMID 34249264, 2021). "SOD2 detoxifies thesuperoxide by converting it into hydrogen peroxide, in physiological conditions as well as in some neurodegenerative diseases,where it can contribute to prevent neurodegeneration." (PMID 31781336, 2019). "Finally, we also found a trend of increase in the expression of mitochondrial Mn-SOD (SOD2), whose expression levels have previously been reported to be altered in PD as well as in other neurodegenerative diseases." (PMID 41436906, 2025). "It is believed that impaired SOD2 is a potential pathogenesis related to oxidative stress in PD and AD, whereas the deficiency or malfunction of CAT is related to the pathogenesis of many age-associated degenerative diseases." (PMID 39273374, 2024). "SOD2 expression is highly relevant to neurodegenerative diseases." (PMID 38706516, 2023). "Oxr1 therefore has much in common with some of the most important antioxidants; proteins such as SOD2 can be lethal when disrupted but neuroprotective when over-expressed in vivo and have therefore been nominated as potential therapeutic targets in neurodegenerative disease." (PMID 22028674, 2011). "In neurodegenerative diseases, an increase rather than a decrease in SOD2 is often observed, which has been interpreted as a compensatory mechanism aiming to counterbalance the increased mitochondrial superoxide production." (PMID 34200581, 2021).
kidney disease (20 papers, 2013 to 2025). "Studies have shown that SOD2 plays an important role in preventing oxidative stress-related diseases, such as inflammation, cancer, cardiovascular diseases, and kidney disease." (PMID 41275592, 2025). "Mitochondrial oxidative stress and biological regulation of SOD2 plays a role in the pathogenesis of kidney diseases." (PMID 33202982, 2020). "SOD2 played a protective role in kidney disease and could be identified as an indicator of severity and prognosis." (PMID 41275592, 2025). "It is tempting to speculate that a more complex and heterogeneous pathophysiology of the kidney disease in subjects with proliferative retinopathy might mask the allelic effects of SOD2." (PMID 24819633, 2014).
cardiovascular diseases (18 papers, 2007 to 2025). "In humans, mutations of mitochondrial antioxidants (e.g., SOD2, catalase, GPx, and TrxR) increase the risk for cardiovascular diseases." (PMID 32424140, 2020). "In cardiovascular disease, SOD2 stands at the forefront against mitochondrial ROS in vascular smooth muscle cells (VSMCs) via its preferential localization to the mitochondria, which conduces to the potential modification of the probability of vascular calcification initiation or progression." (PMID 34777635, 2021). "Of particular interest was the observation that only a few of the most significantly up/downregulated proteins such as the superoxide dismutase (SOD2), HSP90AA1 or GOT1, could be allotted a cardiac-related function, or may have been implicated in cardiovascular disease thus far." (PMID 27711126, 2016).
retinopathy (12 papers, 2007 to 2025). "Of the 14 differentially spliced and expressed proteins, PRPF31 itself was identified, in addition to superoxidase dismutase mitochondrial protein (SOD2) for which reduced expression has been linked to retinopathies." (PMID 30315276, 2018). "SOD2 has been linked to diabetic microvascular problems such as DR and retinopathy." (PMID 35399949, 2022).
metabolic disorders (11 papers, 2016 to 2025). "Under metabolic disorder, higher SOD2 activity in subjects with rs4880-CC might cause higher mitochondrial H2O2 accumulation, leading to oxidative stress-related IR which affect HTG and low HDL-C level." (PMID 31396447, 2019). "The influence of SNPs in SOD2 on redox status, which may affect metabolic diseases, has emerged in recent years." (PMID 36330440, 2022). "As mitochondrial dysfunction caused by metabolic disorders is the main origin of ROS generation in DCM, SOD2 has an extremely pivotal role in regulating ROS homeostasis after being deacetylated from Ac-SOD2 by the effect of several kinds of sirtuins, in which SIRT1 plays a crucial role." (PMID 31210844, 2019). "With the high levels of ROS and lower levels of SOD2 detected in TLR4/NF-κB-activated trophoblasts, our data further elucidated that the TLR4/NF-κB-induced metabolic disorders might inextricably link with the redox disturbances in the PE placentas." (PMID 34804360, 2021).
adenocarcinoma (7 papers, 2000 to 2021). A common cancer characterized by the presence of malignant glandular cells. "Based upon strong SOD2 immunoreactivity in MMs in contrast to adenocarcinomas, and low SOD2 levels in healthy human pleural mesothelium compared to high endogenous levels in MM lines, SOD2 has been proposed as a diagnostic marker for MM." (PMID 20831825, 2010). "SOD1 had markedly higher mRNA levels compared with SOD2 or SOD3, the latter being significantly downregulated in adenocarcinoma tissues." (PMID 29478325, 2019).
bacterial infection (7 papers, 2009 to 2025). "SOD2 expression has been linked to impact immunity against bacterial infections in zebrafish and ROS are known to play a role in the reaction to inflammatory disease." (PMID 35749523, 2022). "SOD2 is a critical regulator of antiviral signaling, while CD36 is known to promote inflammatory responses and phagocytosis, processes involved in the host response to both viral and bacterial infections." (PMID 40355874, 2025). "For the gene SOD2 (ENSG00000112096.19), transcript ENST00000367055.8 (adjusted P-value = 0.029) showed reduced usage, whereas transcript ENST00000538183.7 (adjusted P-value = 0.003) exhibited increased usage in samples from patients with viral compared to bacterial infection." (PMID 40355874, 2025).
cardiac diseases (7 papers, 2018 to 2022). "SOD2 mutations are associated with heart disease and increased risk of malignancies." (PMID 31921313, 2019).
kidney (7 papers, 2005 to 2024). "Conversely, work in the mouse and human kidney suggests that Usp36 interacts with SOD2 in the mechanism of acute kidney injury due to ischaemia." (PMID 38734725, 2024).
neurological disease (6 papers, 2016 to 2025). "However, different levels of SOD2 were detected in neurological diseases and psychiatric disorders in different studies, making it hard to elucidate its importance." (PMID 39838666, 2025).
mitochondrial disease (5 papers, 2015 to 2025). "Moreover, Sod2 deficient mice display multiple biochemical features of mitochondrial disease associated with ROS toxicity." (PMID 26642061, 2015).
inflammation (4 papers, 2019 to 2023). Aberrant reaction of the microcirculation characterized by movement of fluid and leukocytes from the blood into extravascular tissues. "On the contrary, it has been reported in other studies that the loss of heterozygous SOD2 would aggravate chronic intermittent hypoxia-induced lung inflammation and vascular remodeling through the mtROS-NLRP3 signaling pathway." (PMID 34777635, 2021). "Mice with a partial SOD2 deficiency exhibit oxidative stress and renal interstitial inflammation, which accelerates renal senescence and salt-sensitive hypertension." (PMID 30914727, 2019).
benign tumor (3 papers, 2018 to 2021). "Of these, 15 proteins (PRSS8, MK, WFDC2 (HE4), IL-10, SOD2, PARP-1, hK11, PVRL4, MUC-16 (CA125), FR-alpha, CDH3, NTRK3, IL-8, IL-17C, EN-RAGE) were selected from the comparison between OC stage I–IV and benign tumors." (PMID 30519148, 2018).
gastrointestinal tumor (2 papers, 2017 to 2023). "Treatment of GI tumor cells with [curcumin + sildenafil] decreased expression of SOD2 and TRX." (PMID 29245915, 2017).
Immune dysfunction (2 papers, 2020 to 2022). "Immune dysfunction in autistic offspring via superoxide dismutase 2 suppression is found to be induced by maternal diabetes." (PMID 36293620, 2022). "We conclude that maternal diabetes induces immune dysfunction in autistic offspring through SOD2 suppression and oxidative stress in HSC." (PMID 33101089, 2020). "Our results show that maternal diabetes induces epigenetic changes on the SOD2 promoter in HSC and that these kinds of epigenetic changes are inherited in subsequent PBMC, resulting in immune dysfunction." (PMID 33101089, 2020). "We conclude that maternal diabetes induces immune dysfunction in autistic offspring through oxidative stress in HSC and that SOD2 suppression in PBMC can be a sensitive biomarker for ASD diagnosis." (PMID 33101089, 2020). "We conclude that maternal diabetes induces immune dysfunction in autistic offspring through oxidative stress in HSC and that SOD2 mRNA levels in PBMC may be a good biomarker for the diagnosis of ASD patients." (PMID 33101089, 2020).
infectious disease (2 papers, 2019 to 2021). A disorder directly resulting from the presence and activity of a microbial, viral, or parasitic agent in humans. "Additionally, some of these target genes, including SOD2, TNFAIP3, ARG1, SERPINB2, VLDLR, HSPA5, and LCN2, are associated with infectious diseases, suggesting that lncRNAs respond to PCV2 infection by regulating these genes." (PMID 30863688, 2019). "In addition, we analyzed the predicted target genes of differentially expressed lncRNAs, including SOD2, TNFAIP3, and ARG1, all of which are involved in infectious diseases." (PMID 30863688, 2019).
bone disorder (1 paper, 2023). "Both SOD1 and SOD2 have been suggested as therapeutic targets for bone disorders." (PMID 36185749, 2023).
CNS tumors (1 paper, 2022). "Malignant CNS tumors have immunoreactivity to MnSOD (SOD2) in both the intra- and extracellular matrix, despite the fact it is not detected in normal brain tissue." (PMID 36307808, 2022).
disorders of the urinary tract (1 paper, 2023). "Thus, polymorphic variants may play a crucial role in the modulation of SOD2 activity, leading to many disease development, including disorders of the urinary tract." (PMID 37878647, 2023).
musculoskeletal disease (1 paper, 2022). "In the present study, to develop a therapeutic strategy for musculoskeletal disease, we searched for substances that enhanced motor function among functional compounds by in vivo screening using muscle-Sod2-/- mice as a muscle fatigue model." (PMID 36551829, 2022).
respiratory diseases (1 paper, 2020). "As a result, some genes screened out have been actually reported to be associated with respiratory diseases, such as the gene of superoxide dismutase 2 (SOD2)." (PMID 32117613, 2020).
SOD2 also shares sentences with these, for which no sentence is quoted: triple-negative breast carcinoma (7 papers); mesothelioma (5); pancreatic ductal adenocarcinoma (5); Parkinson (5); cardiac arrhythmia (4); ovarian tumor (4); peripheral neuropathy (4); psychiatric disorder (4); asthenospermia (3); atopic dermatitis (3); atrial fibrillation (3); end-stage renal disease (3); Ewing sarcoma (3); gastric tumor (3); Huntington disease (3); hyperuricemia (3); infarction (3); invasive breast carcinoma (3); kidney injury (3); lung disease (3); migraine with aura (3); Arthritis (2); bladder tumor (2); brain disease (2); bronchopulmonary dysplasia (2); chronic atrophic gastritis (2); Chronic Myeloid Leukemia (2); Cockayne syndrome A (2); colon adenoma (2); complication (2).
A further 220 diseases each share a sentence with SOD2 in 2 papers or fewer.